FOXD2-AS1 (FOXD2 adjacent opposite strand RNA 1)
Synonyms: MGC12982
Gene: Long non-coding RNA gene on chromosome 1 (47,432,133 to 47,434,641, reverse strand). Ensembl gene ENSG00000237424.
Diseases named in the same sentence as FOXD2-AS1 in open-access papers:
FOXD2-AS1 is named in the same sentence as 4 diseases in open-access papers, as found by Europe PMC text mining. Sharing a sentence is not in itself a finding about the gene and the disease. The quoted sentences say what the papers report.
bladder cancer (1 paper, 2020). "FOXD2-AS1 (FOXD2 adjacent opposite strand RNA 1) is an oncogenic lncRNA that is overexpressed in bladder cancer and promoted progression and recurrence via forming a positive feedback loop with AKT and E2F transcription factor 1 (E2F1)." (PMID 32760219, 2020).
pterygium (1 paper, 2020). A wedge-shaped fibrovascular lesion arising from the bulbar conjunctiva and extending to the cornea. "Furthermore, we confirmed that the enrichment level of H3K27ac at the FOXD2‐AS1 promoter was notably increased in both HPF‐R cells and recurrent pterygium tissues, resulting in FOXD2‐AS1 up‐regulation." (PMID 33098266, 2020).
cancer (4 papers, 2019 to 2022). A tumor composed of atypical neoplastic, often pleomorphic cells that invade other tissues. "Background and aims: Long non-coding RNA (lncRNA) FOXD2 adjacent opposite strand RNA 1 (FOXD2-AS1) is aberrantly expressed in various cancers and associated with cancer progression." (PMID 33140822, 2020). "FOXD2 adjacent opposite strand RNA 1 (FOXD2-AS1) plays an important role in the pathogenesis of some cancers." (PMID 33318296, 2020). "Long non-coding RNA FOXD2 Adjacent Opposite Strand RNA 1 (FOXD2-AS1) has been widely reported to be implicated in the progression and recurrence of several cancers." (PMID 31024447, 2019). "The lncRNA, FOXD2 Adjacent Opposite Strand RNA 1 (FOXD2-AS1), has been reported to function as an oncogenic lncRNA in several human cancer types." (PMID 31024447, 2019).
FOXD2-AS1 also shares sentences with these, for which no sentence is quoted: tumor (1 paper).